SMAD2 (SMAD family member 2)
Diseases named in the same sentence as SMAD2 in open-access papers (continued):
Sharing a sentence is not in itself a finding about the gene and the disease.
colon carcinoma (continued). "To examine whether the Kv11.1 activator affects TGFβ signaling we monitored phosphorylation of SMAD2/3 on the conserved carboxy-terminal SSXS motif in colon cancer cells that were incubated with NS1643 for different time periods." (PMID 34885136, 2021). "Our research suggested that ADAM8 could be a potential biomarker for the prognosis of colon cancer and induced EMT to promote the invasion of colon cancer cells via activating TGF‐β/Smad2/3 signalling pathway." (PMID 32954649, 2020). "Furthermore, it is important to note that the neutralization of circulating TGF‐β with a pan‐TGF‐β antibody in cachectic 4T1 breast and C26m2 colon cancer mouse models reduces SMAD2 phosphorylation and Zip14 expression in muscles." (PMID 32730698, 2020). "Thus, ADAM8 induced EMT in colon cancer cells through TGF‐β/Smad2/3 signalling pathway, and integrins were the key mediators between the interaction of ADAM8 and TGF‐β." (PMID 32954649, 2020). "Interestingly, we found that Nodal promotes spheroid formation of CCSCs via the activation of Smad2 and Smad3 pathways, suggesting that Nodal is involved in self-renewal of colon cancer stem cells." (PMID 24696849, 2014). "We showed that NRP2 promotes a constitutive Smad2/3 phosphorylation in colon cancer cell lines." (PMID 21747928, 2011). "In addition, we found that ADAM8 could induce EMT to promote colon cancer cell invasion via activating TGF‐β/Smad2/3 signalling pathway." (PMID 32954649, 2020). "Therefore, downregulation of Smad4, or treatment with inhibitors to inhibit TGFβ signaling or Smad2 and/or Smad3 phosphorylation, combined with Dox may be a potential novel strategy with which to treat colon cancer." (PMID 25684678, 2015). "This interaction stimulates SMAD3 phosphorylation and activates the SMAD2-3-4 signaling pathway, resulting in the inhibition of cyclin D1/CDK4 expression and leading to G1 cell cycle arrest in colon cancer cells." (PMID 38338430, 2024). "In colon cancer, GRP78 overexpression promotes epithelial–mesenchymal transition through autocrine TGF-β/Smad2/3 signaling." (PMID 36838713, 2023). "Another study confirmed that overexpression of GRP78 promotes the secretion and expression of TGF-β1 in human colon cancer cell line (DLD1) DLD1 cells, activates the downstream Smad2/3 signal transduction pathway, and promotes cell matrix adhesion and EMT." (PMID 35975844, 2023). "High AQP5 expression can enhance the level of phosphorylated SMAD2, promoting EMT in a colon cancer cell model, whereas suppressed expression of AQP5 can downregulate phosphorylated SMAD2, resulting in downregulated EMT response." (PMID 35847914, 2022). "In conclusion, our study indicated that ADAM8 was an important biomarker for the prognosis of colon cancer and induced EMT to promote the invasion of colon cancer cells via activating TGF‐β/Smad2/3 signalling pathway." (PMID 32954649, 2020). "Since ADAMTS6 induces EMT in colon cancer cells via the NF-κB pathway and acts as an inducer of the TGF-β1/SMAD2/3 pathway, we investigated whether these pathways were affected by ADAMTS6 knockout." (PMID 41465277, 2025). "Moreover, collectively, Nodal signaling pathway promotes the self-renewal of human Colon Cancer Stem cells and mediates carcinogenesis of human CRC in an autocrine manner through Smad2/3 pathway." (PMID 28416736, 2017). "We also observed that NODAL and its receptor ALK-4 were coexpressed in human colon cancer tissues, suggesting that ALK-4 might be involved in the activation of Smad2/3 by Nodal." (PMID 24696849, 2014). "Moreover, we found that ADAM8 could promote the invasion of colon cancer cells and modulate EMT by TGF‐β/Smad2/3 signalling pathway." (PMID 32954649, 2020). "However, unlike in other cancer types such as colon cancer, genetic mutations of its component genes, such as TGFBR2 and SMAD2/4, are rare." (PMID 30181549, 2019).
colon carcinoma (continued). "Thus, escape from the inhibitory signaling activity of TGF-β as seen in other cancers, e.g., colon cancer, is not required in glioblastoma, at least not at the level of Smad2 canonical signaling." (PMID 26918452, 2016). "In addition to Smad2, we systematically identified hsa-miR-140-5p mediated targets via microarray expression analysis by comparing mRNA profiles between the control and hsa-miR-140-5p transfected HCT116 colon cancer cells." (PMID 25980495, 2015).
diabetes (37 papers, 2013 to 2025). "Mechanistic analysis showed that MSC-derived EVs inhibited the TGF-β1/SMAD family member 2 (SMAD2) signaling pathway, which played an important role in the EV-associated improvement in diabetes-induced myocardial injury and fibrosis." (PMID 32708290, 2020). "Thus, we further removed control subjects with a self-reported diagnosis of hyperlipidemia, hypertension or diabetes and then investigated the association between MetS and two key SNPs, namely SMAD2 rs11082639 and TGFBR2 rs3773651." (PMID 29051557, 2017). "Mammalian maternal diabetes results in transient and localized alterations in glycation products, VEGF expression and Smad2 phosphorylation, overlapping with those regions of the developing heart that are most sensitive to diabetes-induced CHD." (PMID 33918884, 2021). "Phosphorylated Smad2 and Smad3 were observed in the glomerular and mesenchymal areas of patients with diabetes, suggesting the important roles of Smad2 and Smad3 in EMT." (PMID 32515466, 2020). "The observed increases in COL4A1, FN1 and phosphorylation of both ERK1/2 and SMAD-2 were prevented when miR-133a was overexpressed in the heart in diabetes." (PMID 24428157, 2014). "TGF-β can activate Smad2 to affect the development of diabetes." (PMID 36588590, 2022). "In addition to the TGFβ1-phospho-Smad2/3 pathway involved in vascular remodeling, we also detected MMPs expression and activity in diabetes and HG-treated VSMC." (PMID 34712140, 2021). "Consequently, we confirmed reduced activity of mTOR signaling components and higher expression of atrophy-related markers typified by FoxO1/atrogin-1/MuRF1 and myostatin-Smad2/3 signaling during the course of diabetes." (PMID 30510624, 2018). "We conclude that inhibition of endothelial cell-derived MEF2A might be beneficial in the prevention of diabetes mellitus-induced cardiac fibrosis by partially inhibiting EndMT through interaction with p38MAPK and Smad2." (PMID 27105518, 2016). "Thus, Krt16 was inhibited in keratinocytes in diabetic wounds due to the up-regulation of Smad2 expression, which is indeed increased in diabetes." (PMID 26428860, 2015). "Our data showed a significant increase in TGF-β1 with further upregulation of phosphorylated SMAD2 and SMAD3 in diabetes, which was indicative of increased inflammation." (PMID 36829889, 2023). "In accordance, mice with beta cell-specific deletion of Smad2 display defective GSIS and overt diabetes along with increased islet proliferation and hyperplasia." (PMID 33765181, 2021). "Curcumin substantially reduced cardiac fibrosis in the STZ rat model of diabetes, seemingly by reducing AGEs, Akt, and TGF-β1 levels, as well as subsequent activation of the Smad2/3 pathway." (PMID 32024054, 2020). "In contrast, treatment with CrPic reversed these changes, highlighting the fact that CrPic prevents diabetes-induced kidney fibrosis and glomerular sclerosis by inhibiting the TGF-β1/Smad2/3 pathway." (PMID 32143429, 2020). "At the whole-animal level, tranilast was also able to prevent fibrosis in a Ren-2 rat STZ model of diabetes, seemingly by reduction of TGF-β1 levels and subsequent Smad2 activation." (PMID 32024054, 2020). "Phosphorylated SMAD2, SMAD3, and TAK1, and increased levels of TβRI and TβRII were observed in HG-cultured NRCFs and diabetes-stimulated CFs, whereas total SMAD2, SMAD3, and TAK1 were not changed." (PMID 41170186, 2025). "Overall, PTβR2I appeared to inhibit the TGFβ1/p-Smad2/3 pathway under normal glucose conditions while having no substantial inhibition effect when the glucose level was as high as that found in diabetes." (PMID 37422462, 2023). "However, as Smad2 also plays an essential role in the glucose-stimulated release of insulin in β cells 16, targeting Smad3 but not upstream TGFBR1 in islets (β cells) may be more favorable for cell replacement treatment of diabetes." (PMID 34987651, 2022).
melanoma (35 papers, 2011 to 2025). A malignant, usually aggressive tumor composed of atypical, neoplastic melanocytes. "It has been reported that SMAD2 is expressed at high level in most cancers, including melanoma, and is associated with the development and progression of tumours." (PMID 39757723, 2025). "Interestingly, in the presence of TGF-β1, YY1 loss increased Smad2 phosphorylation, indicating that melanoma cells display enhanced sensitivity to TGF-β1 when YY1 levels are low." (PMID 35693944, 2022). "Functionally, we show how the TGF-β-SMAD2-CITED1 axis promotes different steps associated with progression: melanoma detachment from keratinocytes, 2D and 3D migration, attachment to endothelial cells, and in vivo lung metastatic initial colonization and outgrowth." (PMID 26526369, 2015). "They demonstrated that tumor cell autonomous hyperstimulation of the TGF-β-SMAD2 pathway is causally related to melanocytic oncogenic progression in the skin and is responsible, at least in part, for the critical switch from radial to vertical growth during human melanoma histogenesis." (PMID 21211030, 2011). "In our study, the higher SMAD2 regulon score in non‐responders compared to responders suggests a potential link between elevated SMAD2 activity and reduced treatment efficacy in mucosal melanoma." (PMID 39757723, 2025). "Beyond its role in immune evasion, CCNB1 also promoted melanoma invasiveness by inducing epithelial–mesenchymal transition (EMT) through the TGF-β-SMAD2/3 signaling." (PMID 40430484, 2025). "Our previous reports on melanoma confirmed that TGFβ stimulated Smad2/3 and Par6/PKC-ι/RhoA pathways stimulated the expression of PKC-ι along with Vimentin." (PMID 33525953, 2021). "Our previous reports confirmed that Smad2/3 and Par6/aPKC/RhoA pathways upregulate the expression of Vimentin along with aPKCs in melanoma cells." (PMID 33525953, 2021). "Our study has shown that the treatment of melanoma cells with rCTII can considerably reduce the expression levels of SMAD2 and SMAD3 genes, which can inhibit metastasis and tumor development." (PMID 33167431, 2020). "In our study, melanoma patients were divided into 5 groups according to varying SMAD2 levels, and then we discovered several immune cells were related to SMAD2 through the immune infiltrates assay." (PMID 33202380, 2020). "The NEAT1/miR-200b-3p/SMAD2 signaling pathway promotes the proliferation and invasion of melanoma cells by activation of EMT." (PMID 33202380, 2020). "It was shown that SMAD2 was significantly upregulated in melanoma tissues compared with benign naevus." (PMID 33202380, 2020). "Taken together, these results confirmed that SMAD2 was directly modulated by miR-200b-3p as a target in melanoma cells." (PMID 33202380, 2020). "CITED1 is the most well-studied in melanoma progression that can be activated by the TGFβ-SMAD2 pathway and promote amoeboid migration of melanoma cells." (PMID 31296175, 2019). "In the current study, we found that melanoma cells augmented the expression of various mesenchymal phenotypic markers, such as Smad2/3, α-SMA, and vimentin, in addition to that of TGF-β, Snail, and Slug, following exposure to Tregs." (PMID 31690033, 2019). "In keratinocytes Filamin A (FLNA), a cytoskeletal SMAD-binding protein, binds SMAD2 for effective TFGβ receptor signaling; accordingly, FLNA-deficient melanoma cells have impaired TGFβ signaling." (PMID 26700622, 2016). "While TGFβ is known to promote EMT99 in epithelial cancers, in melanoma TGFβ signals through SMAD2 and the adaptor CITED1 to support contractile amoeboid migration." (PMID 27158478, 2016). "Melanoma cells treated in vitro showed significant reduction of Nodal protein expression levels and reduction of the activated (phosphorylated) forms of SMAD2 and ERK1/2." (PMID 26460952, 2015). "Phosphorylation of Smad2 at the cluster of serines (245/250/255) was inhibited in the presence of LiCl at the two time points, 2 and 5 hours, and for the three melanoma cell lines." (PMID 23077590, 2012).
melanoma (continued). "Riluzole-treated cells had increased linker phosphorylation of Smad2 at serines 245/250/255 in the five melanoma cell lines tested and of Smad3 at serine 204 in all but the 1205LU cell line." (PMID 23077590, 2012). "As expected, Nodal was able to induce Smad-2 activation in the three melanoma cell lines, and its activity was slightly increased by co-treatment with CR-1." (PMID 21863025, 2011). "Additionally, we found that CCNB1 directly enhances TGF-β production and secretion in melanoma cells, activating the SMAD2/3 pathway to drive EMT and tumor invasion." (PMID 40430484, 2025). "Interestingly, while the TGFβ effects on melanoma cancer stem cell maintenance require the Smad pathway, they also appear to be Smad3/4 specific and Smad2-independent." (PMID 38201651, 2024). "Altogether, these studies are consistent with our present findings in melanoma, suggesting that Smad3 may play a more prominent role in the mediation of the TGFβ tumor-suppressive effects compared to Smad2 in various models of solid tumors." (PMID 38201651, 2024). "Interestingly, our study demonstrated a reduced expression of TGFB1, TFGBR1 and SMAD2 in PRELPhigh vs PRELPlow melanoma cells." (PMID 37730606, 2023). "In vitro and in vivo, we demonstrated that both NEAT1 and SMAD2 could promote the proliferation and invasion of melanoma cells, and these effects were reversed by up-regulating miR-200b-3p." (PMID 33202380, 2020). "Hence, we can deduce that the tumor promoting effects of the NEAT1/ miR-200b-3p/ SMAD2 signaling pathway in melanoma is partly attributed to the activation of EMT." (PMID 33202380, 2020). "In addition, NEAT1/miR-200b-3p/SMAD2 axis promoted melanoma progression by activating EMT signaling pathway and immune responses." (PMID 33202380, 2020). "Collectively, we have good reasons to believe that NEAT1/miR-200b-3p/SMAD2 signaling pathway may promote melanoma partly by immune regulation." (PMID 33202380, 2020). "Hence, we verified the expression of SMAD2 in benign nevus (n=18) and malignant melanoma tissues (n=18) by RT-qPCR." (PMID 33202380, 2020). "Coincidently, high level of SMAD2 was associated with a poor prognosis simultaneously, indicating that SMAD2 may serve as a novel prognostic marker for melanoma along with miR-200b-3p." (PMID 33202380, 2020). "In brief, it displayed that the NEAT1/miR-200b-3p/SMAD2 axis may promote melanoma by activating EMT and immune responses." (PMID 33202380, 2020). "In our study, SMAD2 was found up-regulated in melanoma tissues and cell lines." (PMID 33202380, 2020). "It turned out that NEAT1 was positively correlated with SMAD2 in melanoma tissues (n=18)." (PMID 33202380, 2020). "In melanoma, TGFβ-SMAD2-CITED1 mediated transcription is necessary for melanoma metastasis." (PMID 27586372, 2017). "Moreover, TGFβ-SMAD2-CITED1 signaling axis induces melanoma cell attachment to endothelial cells, lung colonization and metastatic out growth." (PMID 28137308, 2017). "TGFβ-SMAD2-CITED1-mediated transcription promotes melanoma amoeboid invasion." (PMID 27586372, 2017). "We next hypothesized that TGF-β could control actomyosin force in melanoma through SMAD2/CITED1-mediated transcription." (PMID 26526369, 2015). "We previously demonstrated that the two pan-CDK/GSK3 inhibitors, flavopiridol and R547 could inhibit the constitutive linker phosphorylation of Smad2 and Smad3 in melanoma cell lines." (PMID 23077590, 2012). "Therefore, we analysed the effects of CR-1 and/or Nodal on the activation of the Nodal/ALK4/Smad-2 pathway in melanoma cells." (PMID 21863025, 2011). "To address whether the canonical Smad pathway is involved in the mediation of the TGFβ effects on melanoma self-renewal, we generated specific Smad2, Smad3 and Smad4 knockout (KO) in two different melanoma cell lines, A375m and BLM, using CRISPR genomic editing." (PMID 38201651, 2024).